TRAV10 (T cell receptor alpha variable 10)
Description:
V region of the variable domain of T cell receptor (TR) alpha chain that participates in the antigen recognition. Alpha-beta T cell receptors are antigen specific receptors which are essential to the immune response and are present on the cell surface of T lymphocytes. Recognize peptide-major histocompatibility (MH) (pMH) complexes that are displayed by antigen presenting cells (APC), a prerequisite for efficient T cell adaptive immunity against pathogens. Binding of alpha-beta TR to pMH complex initiates TR-CD3 clustering on the cell surface and intracellular activation of LCK that phosphorylates the ITAM motifs of CD3G, CD3D, CD3E and CD247 enabling the recruitment of ZAP70. In turn ZAP70 phosphorylates LAT, which recruits numerous signaling molecules to form the LAT signalosome. The LAT signalosome propagates signal branching to three major signaling pathways, the calcium, the mitogen-activated protein kinase (MAPK) kinase and the nuclear factor NF-kappa-B (NF-kB) pathways, leading to the mobilization of transcription factors that are critical for gene expression and essential for T cell growth and differentiation. The T cell repertoire is generated in the thymus, by V-(D)-J rearrangement. This repertoire is then shaped by intrathymic selection events to generate a peripheral T cell pool of self-MH restricted, non-autoaggressive T cells. Post-thymic interaction of alpha-beta TR with the pMH complexes shapes TR structural and functional avidity.
Synonyms: TCRAV10S1; TCRAV24S1
Gene: T-cell receptor variable (V) gene on chromosome 14 (21,825,472 to 21,826,075, forward strand). Ensembl gene ENSG00000211784.
Subcellular location: Cell membrane
Gene Ontology:
Biological process: response to bacterium
Cellular component: plasma membrane
Homologues: Orthologues: chimpanzee TRAV10 (81% identical), macaque TRAV10 (79% identical), mouse Trav11 (56% identical), mouse Trav11d (56% identical). Paralogues in human: TRAV17 (45% identical), TRAV7 (44% identical), TRAV6 (43% identical), TRAV20 (42% identical), TRAV39 (42% identical), TRAV21 (40% identical), TRAV36DV7 (40% identical), TRAV34 (39% identical), TRAV27 (39% identical), TRAV24 (38% identical), TRAV5 (37% identical), TRAV25 (35% identical), and 11 more.
Diseases named in the same sentence as TRAV10 in open-access papers:
TRAV10 is named in the same sentence as 7 diseases in open-access papers, as found by Europe PMC text mining. Sharing a sentence is not in itself a finding about the gene and the disease. The quoted sentences say what the papers report.
COVID-19 (2 papers, 2022 to 2025). A disease caused by infection with severe acute respiratory syndrome coronavirus 2. "Hospitalized COVID-19 and sepsis cases displayed reductions in the percentage of repertoire occupied by TRAV10, specific to invariant NK T cells, and TRAV1-2 and TRAJ33 usage, in keeping with reductions in MAIT cells." (PMID 35216673, 2022).
primary biliary cholangitis (1 paper, 2025). Primary biliary cholangitis (PBC) is a chronic and slowly progressive cholestatic liver disease of autoimmune etiology characterized by injury of the intrahepatic bile ducts that may eventually lead to liver failure. "For the α chain, Trav10 [S26], Trav16n [S20,26], Trav17 [S27], Trav5‐4 [S26], Traj42 [S20,26] and Traj53 [S26] were associated with Type I diabetes, whereas Trav12‐2 [S28] was associated with primary biliary cholangitis." (PMID 40665793, 2025).
tumor (2 papers, 2013 to 2022). "This correlation is weaker when looking at the TRAV10 and TRBV25-1 genes together with the M2 signature genes in the tumor site (R = 0.63) and inexistent in the normal adjacent tissue (R = 0.064)." (PMID 35885028, 2022).
TRAV10 also shares sentences with these, for which no sentence is quoted: cancer (1 paper); colon adenocarcinoma (1); Sepsis (1); Type I diabetes (1).